IL6 (interleukin 6)
Diseases named in the same sentence as IL6 in open-access papers (continued):
Sharing a sentence is not in itself a finding about the gene and the disease.
infection (continued). "Several biomarkers such as C-reactive protein (CRP), interleukin 6 (IL-6), and procalcitonin (PCT) are widely used in clinical practice for the early diagnosis and prediction of clinical outcomes in patients with infection." (PMID 38892234, 2024). "It has to be noted that the initial response of the innate immune system to injury and infection is reflected by TNF-α and IL-6." (PMID 39200283, 2024). "In this study we observed lower bacterial burden at the infection site of Ppara-/- mice compared to C57BL/6 mice, but the levels IL-6 and TNF-α elicited by S. aureus infection were equally robust in both mouse lines." (PMID 38601738, 2024). "To investigate the impact of CASK on cytokine production, we measured the levels of IFN-β, IFN-α, IFN-6, TNF-α, IL-6, IL-1β and IP-10 in the culture supernatant of macrophages at 12 h post-H5N1-IAV (MOI=1) infection." (PMID 39850902, 2024). "Expression of IL-6, IL-8 (CXCL8), CXCL1, CXCL2, and CCL-20, which are known to be expressed in the respiratory epithelium upon infection, was assessed." (PMID 38756230, 2024). "M1 macrophages are pro-inflammatory macrophages that clear pathogens and produce inflammatory mediators such as IL-1β, IL-6, and TNF-α during infection and inflammatory responses." (PMID 39123188, 2024). "In three of them, we observed an increase in IL6 and IL8 transcriptions upon infection, compared with the parental wild-type cell line." (PMID 39345209, 2024). "Additionally, a significant age-related increase in human and rhesus monkey plasma IL-6 and IL-1β, even in the absence of inflammation or infection, indicates that proinflammatory cytokines IL-6 and IL-1β are important mediators of the age-associated increase in intestinal permeability." (PMID 38785555, 2024). "During in vivo infection, pigs infected with highly virulent strains of ASFV exhibit elevated systemic production of IFN, TNF-α, IL-1α, IL-1β, and IL-6, mainly facilitated by NF-κB or alternative transcription factors." (PMID 38846950, 2024). "After infection of BMDMs and treatment during 24 h, we observed a significant decrease in the stimulation of TNF-α and IL-6 when the yeast cells were treated with TRB and 20 and 40 μg/mL of ML, when compared with untreated cells (1:10)." (PMID 39194287, 2024). "In comparison to uninfected mice, the levels of IL-1β, IL-6, IL-12p70, TNF-α, CCL2, CXCL2, GM-CSF, and G-CSF were significantly increased in both PLF and serum after infection." (PMID 38951957, 2024). "A serum IL-6 level of ≥ 13 pg/mL had a 90.9% positive predictive value for infection, while ≤ 8 pg/mL had a 92.1% NPV, indicating infection absence." (PMID 39493345, 2024). "In details, ELISA results revealed an intra-specific variability of IL-6 production between the two strains of M. bovis tested (SB0120 and SB1564), with a greater secretion observed in the M. bovis SB1564 infection." (PMID 38399810, 2024). "This leads to an upregulation of IFN‐γ, IL‐6, TNF‐α, and other cytokines and chemokines, ultimately improving infection control and survival rates." (PMID 39492834, 2024). "In this study, we found that murine B. abortus 2308 infection increases IFN-γ, IL-6, IL-12, and TNF-α." (PMID 38794208, 2024). "Infection triggered a T helper-type 1 immune response supported by the detection of pro-inflammatory cytokines such as IFN-γ, IL-1β, IL-6, IL-12p40 and IL-17 in the supernatant of lung homogenates." (PMID 38198478, 2024). "Lung macerate supernatants showed an increase in the concentration of IL-6, RANTES and TNF-α in the HIV single infection group compared to the uninfected control animals, as well as the Mtb single infection group." (PMID 38799434, 2024). "The test detects two recognized markers of infection, Matrix MetalloProteinase-8 (MMP-8) and Interleukin-6 (IL-6), in a lateral flow assay using peritoneal dialysate taken from the dialysis effluent." (PMID 38893639, 2024).
infection (continued). "Here, we observed that the ratios of Th2 to Th1 cytokines, specifically anti-inflammatory cytokines (IL-4, IL-6, and IL-10) relative to IFN-γ, remained stable throughout the infection." (PMID 39061002, 2024). "Our data shows an increase in TNF-α and IL-6 but a decreased expression in IL-1β and IL-8 post DLD-1 infection." (PMID 39427065, 2024). "The gene expression levels of the pro-inflammatory cytokines, including IL-6, TNF-α, and CCL2, were significantly elevated in the infection group compared to the control group (P < 0.01 and P < 0.05, respectively; n = 5; Tukey test)." (PMID 38233485, 2024). "Biomarkers for early infection diagnosis, including procalcitonin (PCT), Interleukin-6 (IL-6), and (CRP), have been extensively studied." (PMID 38956649, 2024). "Smurf1−/− BMDMs secreted similar levels of IL-6 compared to MHV-A59-infected wild-type in all periods evaluated, with the exception of 48 h post-infection, when IL-6 secretion by Smurf1−/− BMDMs was lower, compared to wild-type infected cells." (PMID 39452742, 2024). "The infection triggers an inflammatory response characterized by the release of cytokines such as IL-6 and TNF-alpha, which recruit immune cells to the infection site." (PMID 39125464, 2024). "To assess the efficacy of inflammatory markers for early infection diagnosis in CAR-T therapy patients, we measured serum inflammatory indicators (PCT, IL-6, and CRP) at the onset of fever following CTI." (PMID 38956649, 2024). "They observed that after infection withSARS-CoV-2, endothelialcells from infected lung-on-chips showed significant upregulationof TNF-α, IL6, and IFN-β and more modest increase ininterferon-λ1 (IFNL1) and IFNL3 expression." (PMID 38559954, 2024). "shows that the IL-6 and TNF-α levels increase during infection or tissue injury, and their low expression levels are of great significance to DF wound healing." (PMID 38464966, 2024). "Among its antimicrobial mechanisms of action, HBD-2 was also found to promote proinflammatory mediators, including CCL2, IL-6, IL-10 and CXCL10, to fight off infections." (PMID 38886736, 2024). "For the gene expression analyses, the levels of interleukin (IL)-6 and C-X-C Motif Chemokine Ligand 2 (CXCL2) were significantly upregulated in the infection group (P < 0.001 and P < 0.01, respectively; n = 5; Tukey test) compared to the control." (PMID 38233485, 2024). "Nectin-1 was redistributed, at the protein level, in adjacent uninfected cells surrounding infection, inducible by CCL3, IL-8 (or CXCL8), and possibly CXCL10 and IL-6, thus facilitating spread." (PMID 38857290, 2024). "Post-infection, RTX-treated mice showed reduced inflammatory cytokine levels, including IL-1β, IL-6, and TNF." (PMID 39414787, 2024). "Upon infection, the EBV dUTPase protein induces the expression of pro-inflammatory cytokines such as IL-6 and IL-1β in microvascular endothelial cells and microglia, as well as TNF-a in astrocytes." (PMID 38248274, 2024). "Compared to the control group, the expression levels of IL-1β, IL-6, and TNF-α in the PCV4-inoculated group continuously increased during the infection period, peaking at 21 days." (PMID 39135875, 2024). "Multivariate analysis showed that elevated IL-6 and PCT levels on POD 3 were independent factors for postoperative infection complications." (PMID 38504206, 2024). "Subsequently, we assessed the expression levels of the proinflammatory cytokines IL-6 and TNF-α in the cell culture supernatant at 2, 4, and 6 hours post-infection." (PMID 38912723, 2024). "Overall, our results suggest that Gal‐1 reduces TNF‐α, IL‐6, IL‐1β, MCP‐1, RANTES‐ MIP‐1,α, and IL‐8 secretion in the human fetal membranes stimulated with LPS, mimicking an intraamniotic infection." (PMID 39575516, 2024). "Analysis of cytokines indicated a global PCLS age-effect and PAO1 infection-effect for CXCL1, IL-6, and IL-1β, while for TNF-α only a global infection-effect was observed." (PMID 38178102, 2024).
infection (continued). "To investigate the impact of MNK1 knockout on pro-inflammatory cytokine production in J774A.1 cells during Vv infection, we compared the levels of TNF-α and IL-6 in parental and MNK1−/− cells infected by Vv." (PMID 38980024, 2024). "The expression of cytokine and chemokine genes, IL-1β, IL-6, TNF-α, IFN-γ, IL-12, and CXCLi1 in the liver of chickens were detected 3 to 5 days post-infection." (PMID 38846788, 2024). "We selected five cytokines, including CXCL-1, CXCL-2, IL-6, IL-8, and CCL-20, and determined their expression levels 24 h after infection using qPCR." (PMID 38756230, 2024). "Upon VSVΔ51 infection, 4-OI inhibited the nuclear translocation of RELA (p65) and reduced the release of IL-6 in the supernatants of virus-infected cells." (PMID 38750019, 2024). "IL-6, MIP-3α and MIP-1α levels were shown to significantly increase over the course of the infection, but with unique induction kinetics." (PMID 38672079, 2024). "Numerous proinflammatory cytokines exhibited decreased expression in Omicron-infected BSs compared to those infected with the WT virus, including IL6, CXCL1, CXCL2, and IL1B, which play a crucial role in attracting immune cells to infection sites." (PMID 38741604, 2024). "First, IBV DMV/1639 infection exhibited a robust induction of innate immune responses, evidenced by heightened expressions of IFN-α, IFN-β, IL-1β, IL-6, and iNOS mRNA." (PMID 39472003, 2024). "During blood-stage infection, pro-inflammatory cytokines such as IFN-γ, TNF-α, IL-6 and IL-8 are crucial for controlling the growth of parasites." (PMID 38689233, 2024). "For example, IL-1β and TNF-α, produced in response to infection and tissue damage, stimulate TLR4, leading to IL-6 secretion—a pleiotropic cytokine that plays a crucial role in acute-phase protein secretion." (PMID 39273468, 2024). "Taken together, ITA and its isomers MES and CTC have an overall similar immunomodulatory effect on production of the cytokines IL6, TNFα, IL1β and IL10 in response to infection with C. burnetii." (PMID 39156902, 2024). "Infection with BRSV leads to an increase in several cytokines and chemokines in circulation, including IL-6, TNF-α, IL-18, chemokine-x-c motif ligand (CXCL8), CCL2, CCL3, and CCL5, mediating the subsequent influx of leukocytes, predominantly neutrophils." (PMID 39599867, 2024). "The levels of MIP-1α, MIP-1β, IL-6, RANTES, MCP-1, and CXCL1 were significantly reduced in Adam9 KO compared to WT mice after infection." (PMID 38755212, 2024). "Our investigation suggests that despite potential interference from factors like CRS, biomarkers such as PCT, IL-6, and CRP hold promise for early infection detection, particularly in severe cases." (PMID 38956649, 2024). "In a recent study, the steep increase in the expression of the proinflammatory cytokines IL-6, IL-8, and IFN-γ and that of a regulator cytokine, IL-10, was detected at 5 h after infection." (PMID 38787238, 2024). "As ITA is an immunomodulatory agent, we measured the pro-inflammatory cytokines TNF, IL-6, and IL-1β, and the anti-inflammatory cytokine IL-10 in cell culture supernatants 24 hours after NMII infection of Acod1+/- and Acod1-/- BMM." (PMID 39156902, 2024). "To further improve the accuracy of predicting postoperative infection, we analyzed the value of PCT combined with IL-6 in predicting postoperative infection." (PMID 38504206, 2024). "Inflammatory markers, such as C-reactive protein (CRP), interleukin-6 (IL-6), and tumour necrosis factor-α (TNF-α), have been shown to increase dramatically in response to infection, tissue damage, and active disease." (PMID 38956273, 2024). "Our report is the first to show the expression profile of inflammatory biomarkers (IL-1β, IL-6, TNF-α, IL-18) in four tissues after infection with L. europaeus—with two genotypes simultaneously." (PMID 39273479, 2024).
infection (continued). "In particular, Il-6 was significantly upregulated after 6 h of infection (MOI = 1:10, 1:1, 10:1, and 100:1) and 12 h infection (MOI = 1:1 and 100:1) (p < 0.05)." (PMID 38927100, 2024). "We assessed routine indicators of infection in the enrolled patients, including CRP, PCT, IL-6, and SAA levels." (PMID 39533550, 2024). "A number of studies indicate that let-7a/b/c/d/e/f/g/i are frequently downregulated by the HBx protein in early-stage infection in the PME and therefore can fail to modulate inflammatory proteins like Il-6 and IL-10." (PMID 38256049, 2024). "Post-infection treatment with varying OMT doses revealed a distinct modulation pattern of IFN-α, IFN-β, IL-6, and TNF-α levels, indicating effects shaping the antiviral immune response." (PMID 38731436, 2024). "Similar to the findings in our transcriptional analysis, we found increased TNFα (P = 0.028) and CXCL1 (P = 0.0056) in the ECRG4 KO mouse infection, as well as a trend towards increased CXCL2, IL1β, and IL6." (PMID 39509414, 2024). "The research also indicated a significant increase in pro-inflammatory cytokines, such as IL-6 and TNF-α, following acute stress exposure, which is crucial for necessary inflammatory processes during physical injuries or infections." (PMID 39518533, 2024). "Hence, locally produced pro-inflammatory cytokines such as tumor-necrosis factor alpha (TNFα), interleukins (IL)-1 or IL-6 and prostaglandin E2 could move via systemic circulation to distant organs and contribute to cellular disbalance far away from the side of infection." (PMID 39717783, 2024). "Next, we found that the expression of proinflammatory mediators (IL‐6, IL‐8, IP‐10, MCP‐1, MIP‐1α, and TNF‐α) was substantially increased in cells that had been stimulated with IFN‐β before the infection with the H1N1 virus." (PMID 38617435, 2024). "IL-8 and CCL3 were produced at significantly increased levels compared to mock infection, with trends for IL-6, CXCL1, and CXCL10, at 12 h post-infection." (PMID 39599904, 2024). "The infection with S. pneumoniae augmented the concentrations of both IFNs (IFN-β and IFN-γ), the inflammatory cytokines IL-6 and IL-12, as well as the immunoregulatory cytokines IL-27 and IL-10 in AMphs cultures." (PMID 39766307, 2024). "The infection stage group had higher content of PCT, TNF‐α, and IL‐6 and lower content of Beclin‐1 and LC3 than the infection control group (p < .001)." (PMID 38577990, 2024). "The cytokine response to infection with MR766 or PRVABC59 is mainly limited to CXCL10, IL-6/8/12, and CCL5." (PMID 39057782, 2024). "Macrophages secret pro-inflammatory cytokines such as interleukin-1 (IL-1), interleukin-6 (IL-6) and tumour necrosis factor-alpha (TNF-α) aiming to fight the infection." (PMID 39226928, 2024). "Pro-inflammatory interleukins, such as IL-1β, IL-6, and TNF-α, are key players in initiating and amplifying immune responses during infection or tissue injury." (PMID 38251210, 2024). "After infection with H. pylori, the gene expressions of abundant proinflammatory cytokines in AGS cells, including TNF-α, IL-6, COX-2, IL-8, and IL-16, were upregulated significantly (p < 0.05)." (PMID 38891033, 2024). "The mRNA expression of both IL-6 and TNF-α was found to be suppressed in the lungs of vaccinated hamsters as compared to unvaccinated infection control." (PMID 39911577, 2024). "ROC curve analysis was performed to evaluate the predictive ability of IL‐6, PCT, and CRP absolute concentrations against infection efficacy." (PMID 38967137, 2024). "Based on IL-6 and TNF-α secretion, the data suggest that compared to infection with RB51, the inflammatory response induced by S2308 in RAW264.7 cells is more delayed." (PMID 38464511, 2024). "Lung tissue from the mice revealed four of these, IL1-RA, IL-6, CCL2, and IL-12p40, to be upregulated with low-inoculum infection by QPCR." (PMID 39474424, 2024).
infection (continued). "In this study, the levels of IL-1β, IL-6, IL-10, and TNF-α in the sera of mice were measured three days after infection with Lm928, ΔEIIB, and CΔEIIB." (PMID 39057985, 2024). "Our analysis revealed that LV infection considerably increased the expression of TNF-α, IL-β, and IL-8 genes while levels of IL-6 were unchanged in 22RV1 cells relative to the uninfected cells." (PMID 39427065, 2024). "In our study, we found that TLR7 was involved in the immunopathogenesis of infection with RABV, and the expression of CCL2, CXCL10 and IL-6 were significantly increased in the terminal stage of infection with RABV." (PMID 39273091, 2024). "And the levels of IL-6 and TNF-α were significantly higher in serum and lungs of Mettl3 cKO mice than those of Mettl3 WT mice upon infection with P. multocida, S. aureus, and M. pneumoniae." (PMID 38182816, 2024). "In contrast, higher levels of pro-inflammatory factors like IL-6, GM-CSF and CXCL1 were observed in BALF along with lower amounts of IFNγ and IFNγ-producing T-cells one day post-infection." (PMID 39472590, 2024). "Furthermore, this is the first time a specific study has been done on the effects IL-6 has on microglia and astrocyte responses to cerebral cryptococcosis in vivo, which is an important step forward to understanding the way Cn establishes and develops an infection in the brain environment." (PMID 39334365, 2024). "We measured the abundance of TNF-α and IL-6 in the thigh muscle tissue and found similar levels of both cytokines in C57BL/6 and Ppara-/- infections." (PMID 38601738, 2024). "The results showed that on both days 3 and 5, the 10 mg/kg or 100 mg/kg probenecid-treated mice had significantly (p < 0.05) reduced IL-6, TNF-α, and IL-1β when compared to the infection control mice." (PMID 38275962, 2024). "Based on the ROC curve, the accuracy of IL-6, PCT, CRP, and WBC levels on PODs 3 and 5 in predicting postoperative infection was calculated." (PMID 38504206, 2024). "From the seventh day (October 19), the patient’s body temperature increased again and continued, C-reactive protein, interleukin-6, and procalcitonin continued to rise, and WBC continued to decrease, indicating an aggravation of infection." (PMID 39093790, 2024). "Post-infection with uropathogenic Escherichia coli (UPEC), cytokines such as IL-1β, IL-6, and IFN-γ are significantly suppressed, while the bacterial load in the lungs and spleens of wild-type mice is substantially higher than in ATF3 knockout mice." (PMID 38255898, 2024). "Similar to ROSS strain infection, the expression of TNF-α, IL-6, CCL-2, and IL-10 was reduced upon etravirine treatment compared with DMSO treatment under the LR2006 OPY1 strain challenge." (PMID 39339151, 2024). "Specifically, wild-type PRRSV-2 increased activation of NF-κB and enhanced induction of IL-6, IL-8, and TNF-α in coinfected cells compared to single infection with S. suis." (PMID 38547254, 2024). "M1 macrophages can control infection by releasing a wide spectrum of factors including IL-1β, TNF-α, IL-6, and iNOS expression." (PMID 37227688, 2024). "Microarray analysis of host mRNAs after lytic infection of KSHV revealed that several mRNAs, including IL6, escape decay." (PMID 38321453, 2024). "In an established in vitro system that mimics blood stage infection, elevated proinflammatory TNF and IL-6 cytokine production is correlated with increased mono- and tri-methylated H3K4 levels." (PMID 38316918, 2024). "Concentrations of C-reactive protein (CRP), procalcitonin (PCT), interleukin-6 (IL-6), and tumor necrosis factor-alpha (TNF-α) in plasma and bronchoalveolar lavage fluid (BALF) measured at 6 h after infection were notably higher than those at 54 h." (PMID 38323827, 2024). "Inflammatory cytokines, including interleukin 6 (IL-6), interleukin 1β (IL-1β), and tumor necrosis factor-alpha (TNF-α) are secreted by microglia within the brain in response to injury and infection." (PMID 39000602, 2024).